IQCF6 (IQ motif containing F6)
Tractability: No criterion of Open Targets' tractability assessment is met for any kind of drug.
Gene: Protein-coding gene on chromosome 3 (51,778,561 to 51,779,241, reverse strand). Ensembl gene ENSG00000214686.
Gene Ontology:
Molecular function: calmodulin binding
Genetic constraint (gnomAD): Loss-of-function variants: 17 observed, 19.74 expected, observed/expected ratio (o/e) 0.86, 90% interval 0.59 to 1.29. The upper end of that interval is the gene's LOEUF score, 1.29, which puts it in group 5 of 6, group 1 being the genes least tolerant of losing a copy. Missense variants: 169 observed, 197.16 expected, observed/expected ratio (o/e) 0.86, 90% interval 0.75 to 0.97. Synonymous variants: 64 observed, 70.58 expected, observed/expected ratio (o/e) 0.91, 90% interval 0.74 to 1.12.
Homologues: Orthologues: pig IQCF6 (89% identical), dog IQCF6 (82% identical), guinea pig IQCF6 (82% identical), rabbit IQCF6 (81% identical), mouse Iqcf6 (75% identical), rat Iqcf6 (75% identical), macaque IQCF6 (73% identical), chimpanzee IQCF6 (71% identical). Paralogues in human: IQCF2 (45% identical), IQCF5 (42% identical), IQCF1 (41% identical), IQCF3 (40% identical).
Diseases named in the same sentence as IQCF6 in open-access papers:
IQCF6 is named in the same sentence as 3 diseases in open-access papers, as found by Europe PMC text mining. Sharing a sentence is not in itself a finding about the gene and the disease. The quoted sentences say what the papers report.
Obesity (2 papers, 2021 to 2025). Accumulation of substantial excess body fat. "GWAS have identified four of these (INPP5A, ZDHHC2, IQCF6, and PRKCH) to be associated with BMI or obesity." (PMID 40892850, 2025). "The amount of DE mRNAs of obesity in VAT was 136 (35 for overweight, 54 for obesity, and 61 for obesity with MS), and only 2 mRNAs (IQCF6 and FRAG1) were shared by all these 3 obesity components as shown in Venn diagram." (PMID 34621242, 2021).
IQCF6 also shares sentences with these, for which no sentence is quoted: cancer (1 paper); tumour diseases (1).